HIF1A (hypoxia inducible factor 1 subunit alpha)
Diseases named in the same sentence as HIF1A in open-access papers (continued):
Sharing a sentence is not in itself a finding about the gene and the disease.
lung adenocarcinoma (continued). "In addition, our analysis of TCGA data on lung adenocarcinoma revealed that elevated expression of hypoxia-inducible factor 1A (HIF1A), lactate dehydrogenase A (LDHA), lactate dehydrogenase B (LDHB) and SLC16A1 is significantly correlated with poor prognosis." (PMID 34150616, 2021). "In order to investigate whether Huaier can inhibit the energy metabolism of lung adenocarcinoma cells through the PI3K/AKT/HIF‐1α signalling pathway, we administrated the activator and the inhibitor of the PI3K/AKT pathway." (PMID 33377619, 2021). "In A549 lung adenocarcinoma cells exposed to cadmium, HIF1α has been shown to upregulate the expression level of the intracellular domain (ICD) but not the transmembrane subunit (NTM) of NOTCH1, and the regulation is independent of the HIF1α transcriptional activity." (PMID 33015064, 2020). "According to the data obtained from the TCGA database, EHD1 expression was positively correlated with β2AR expression and the expression of the downstream gene hypoxia-inducible factor (HIF)-1α in lung squamous cell carcinomas and lung adenocarcinoma in the TCGA cohort." (PMID 31023336, 2019). "Importantly, we experimentally validate that an approved cardiac arrhythmia and heart failure drug, ouabain, shows potential antitumor activities in lung adenocarcinoma by uniquely targeting a HIF1α/LEO1-mediated cell metabolism pathway." (PMID 31375661, 2019). "Because MPT0B098 can inhibit HIF-1α mRNA and protein expression in the human lung adenocarcinoma cell line A549, we speculated that this compound inhibits HIF-1α expression and suppresses EMT in OEC-M1 cells." (PMID 29592811, 2018). "NRF2 has been shown to activate HIF1α via TRX1 in lung adenocarcinoma A549 cells." (PMID 26904936, 2016). "In vitro studies were conducted to analyze the expression levels of transforming growth factor-β1 (TGF-β1), hypoxia-inducible factor 1 (HIF-1α) and basic fibroblast growth factor (bFGF) in lung adenocarcinoma A549 cells, using the antiangiogenesis drug Endostar combined with radiotherapy." (PMID 24669250, 2014). "We investigated whether controlling HIF-1α expression regulated apoptosis of the lung adenocarcinoma cell line, A549, during hypoxia, and whether this effect of HIF-1α was dependent upon glycolysis." (PMID 16438736, 2006). "However, we did not observe any significant association for HIF-1α expression in lung adenocarcinoma (LUAD) and prostate adenocarcinoma (PRAD) tissues." (PMID 33154192, 2020). "However, it is not known whether enhanced fructose utilization in AML cells and lung adenocarcinoma is enabled by a HIF-1α-mediated switch to KHKC expression." (PMID 32733884, 2020). "Therefore, inhibiting HIF1α in combination with chemotherapy may offer a novel treatment target for lung adenocarcinoma to prevent both cancer proliferation and EMT." (PMID 29568357, 2018). "Inhibition of PIMT and HIF1α may be a novel treatment target for lung adenocarcinoma." (PMID 29568357, 2018). "HIF1A and SLC2A1 expression was significantly higher in lung adenocarcinoma tissues than in adjacent normal tissues." (PMID 39858431, 2024). "Solanidine, a derivative of solanine, has shown itself to be effective in drastically attenuating the levels of HIF-1α and VEGF in human lung adenocarcinoma (A549) cells." (PMID 39124760, 2024). "We performed an expression analysis of HIF1A, and SLC2A1 in lung adenocarcinoma using the CPTAC dataset." (PMID 39858431, 2024). "In lung adenocarcinoma cells, TRIB3 knockdown decreased levels of HIF-1α, indicating a feedback loop between TRIB3 and HIF-1α, where one can regulate the other." (PMID 38896446, 2024). "Lung adenocarcinoma cells (LAC) treated with low-dose CdCl2 were found to have upregulated VEGF expression and secretion in addition to having an increase in HIF1-α expression." (PMID 37593220, 2023).
lung adenocarcinoma (continued). "The genetic alterations and gene expression changes in the BIRC5, HIF1A, and FLT4 oncogenes in lung adenocarcinoma (LUAD) were analyzed using muTarget software." (PMID 37509650, 2023). "The findings were further confirmed in lung adenocarcinoma samples, in which GRK6 expression levels negatively and positively correlate with HIF1α expression (P = 0.015) and VHL expression (P < 0.0001), respectively." (PMID 34136390, 2021). "To validate this axis in clinical samples, we downloaded and analyzed the gene expression profiles of HIF1A, CASC15, SOX4, and CTNNB1 (β-catenin) in two lung adenocarcinoma cohorts from TCGA database." (PMID 33407675, 2021). "The findings were further confirmed in lung adenocarcinoma samples, in which GRK6 expressions negatively correlate with HIF1α protein levels." (PMID 34136390, 2021). "HIF-1α, NRP1 expression, and VM in lung adenocarcinoma (LUAD) patient samples were examined by immunohistochemical staining." (PMID 33850110, 2021). "We found similar HIF stabilization in A549 lung adenocarcinoma epithelial cells and HMEC-1 human dermal microvascular endothelial cells seen by HIF-1α target gene induction and increased HIF-1α protein levels, suggesting a more universal response beyond IECs." (PMID 34190032, 2021). "Meanwhile, we also identified the consensus AK4 metabolic gene signature between the GSE31210 lung adenocarcinoma dataset and TCGA LUAD dataset and found that HIF-1α was again significantly activated, with an activation z score of 4.098." (PMID 30696468, 2019). "b Analyses of TCGA lung adenocarcinoma and lung squamous cell carcinoma samples show that EHD1 expression is positively correlated with HIF1-α expression." (PMID 31023336, 2019). "Analysis of these data revealed that Daam2 expression was positively correlated with HIF1α and pAkt protein expression across this cohort of malignancies, with GBM and lung adenocarcinoma also showing the strongest positive correlation." (PMID 29053101, 2017). "Of these, 4 genes (GLUT1, HK-II, HIF-1α, and CAIX) showed positive correlations between their expression levels monitored by CAGE with SUVmax across 62 lung adenocarcinomas." (PMID 28422979, 2017). "We previously demonstrated that BAs induced destabilisation of HIF-1α not only in IB3-1 and S-9 epithelial cells but in A-549 lung adenocarcinoma cells." (PMID 27416726, 2016). "High expression levels of HIF-1α, CXCR4 and SDF-1α were also detected in both lung adenocarcinoma and squamous cell carcinoma." (PMID 25843954, 2015). "The expression levels of HIF-1α, COX-2 and E-cadherin were determined in 10 cases of normal lung issue and in 45 cases of issue of lung adenocarcinoma by immunohistochemical method." (PMID 21426663, 2011). "The aim of this study is to investigate the clinical significance of the expression of HIF-1α, COX-2, E-cadherin in patients with lung adenocarcinoma and the internal relationship among them." (PMID 21426663, 2011). "The positive expression rate of HIF-1α and COX-2 was 60% (27/45) and 40% (18/45) respectively in 45 cases of lung adenocarcinoma, was null in 10 cases of normal lung issue." (PMID 21426663, 2011). "The overexpression of HIF-1α and COX-2 and the downregulation of E-cadherin is found in lung adenocarcinoma." (PMID 21426663, 2011). "In the present study, we examined the expression of HIF-1α and survivin in tumor tissue from patients with non-small cell lung cancer (NSCLC) as well as in a NSCLC cell line derived from human lung adenocarcinoma (A549)." (PMID 19245702, 2009). "The correlation between the expression of MIF and HIF-1α was validated in driver gene-negative lung adenocarcinoma patients, and the result revealed a significant positive correlation between the expression levels of MIF and HIF-1α in tumor tissues." (PMID 41210694, 2025). "HIF1A expression was correlated with CEBPB and SLC2A1 in lung adenocarcinoma." (PMID 39858431, 2024).
lung adenocarcinoma (continued). "Our study showed an increase of hypoxia-induced gene expression and HIF1α expression in GRK6 knockdown cells, this suggests that GRK6 knockdown may induce EMT in lung adenocarcinoma." (PMID 34136390, 2021). "IAV H1N1 infection of human lung adenocarcinoma epithelial cells stabilizes HIF-1α in normoxic conditions but does not increase HIF-1α mRNA transcription." (PMID 33135539, 2020). "However, in lung adenocarcinoma (LUAD), c-Myc expression was correlated with HIF-1α and Glut1, and the expression of HIF-1α, EGFR, and Glut1 was related to each other in LUAD." (PMID 30967777, 2019). "Searching for novel pharmacological inhibitors for HIF1α, the administration of the indoline sulfonamide MPT0B098 a novel small-molecule inhibitor of microtubule polymerization to lung adenocarcinoma A549 cells efficiently impaired HIF1α-triggered gene expression." (PMID 27582706, 2016). "Although HIF-1α was found to be protective against hypoxia-induced apoptosis in cardiomyocytes, we instead found that increased HIF-1α expression further exacerbated apoptosis in A549 lung adenocarcinoma cells." (PMID 16438736, 2006). "We speculate that the presence of a MIF/HIF-1α positive feedback regulatory loop impacts the development of driver gene-negative lung adenocarcinoma through glycolysis mechanisms." (PMID 41210694, 2025). "We examined serial sections of human H460 lung adenocarcinoma xenograft tumors resected from athymic mice for expression of PFKFB4 and PFKFB3 and correlated the expression levels of these proteins using carbonic anhydrase IX, a potent transcriptional target of HIF-1α, as a hypoxia marker." (PMID 25115398, 2014). "By staining paraffin sections of lung adenocarcinoma, we found that the VECs with PD-L1 overexpression simultaneously revealed higher expression of VEGFA, HIF-1α, and microvascular density compared with negative group." (PMID 32366856, 2020).
leukemia (83 papers, 2011 to 2025). A malignant (clonal) hematologic disorder, involving hematopoietic stem cells and characterized by the presence of primitive or atypical myeloid or lymphoid cells in the bone marrow and the blood. "It has been confirmedthat hypoxia regulates leukemia progression and causesresistance to radiotherapy and chemotherapy.HIF-1α is a key regulator of the hypoxic response and amajor oxygen homeostasis regulator." (PMID 36680478, 2023). "The drug screen revealed that echinomycin, an inhibitor of HIF1A, can effectively attenuate the leukemia phenotype caused by KRASG12V." (PMID 34580712, 2022). "Our group and others have reported that the BM microenvironment in leukemia is hypoxic with associated stabilization of hypoxia-inducible factor 1 alpha (HIF-1α) in leukemic cells." (PMID 32695673, 2020). "We have also shown here that in the leukemic cells, high AA inhibited HIF-1α transcription by blocking transcriptional activation of NF-κB, which is also constitutively activated in many types of leukemia and is associated with leukemic progression." (PMID 23626851, 2013). "In summary, across different types of leukemia, HIF1α has been implicated in the regulation of LSCs maintenance as well as in promoting leukemia dissemination, at times via transcriptional programs reminiscent of epithelial to mesenchymal transition in neoplastic epithelial cells." (PMID 36059690, 2022). "The intracellular formation of hypoxia-indicative pimonidazole adducts, and associated stabilization of HIF-1α in leukemia cells, could result from local oxygen depletion due to high rates of leukemic cell proliferation." (PMID 32695673, 2020). "Interestingly, the accelerated initiation of leukemia due to HIF2α loss was further heightened by the concomitant genetic deletion of HIF1α." (PMID 30781787, 2019). "Moreover, the authors also showed that high dose ascorbate markedly inhibited the expression of HIF-1α in leukemic cells by blocking the transcriptional activation of NF-kB, constitutively upregulated in many types of leukemia and associated with leukemic progression." (PMID 35938170, 2022). "In acute promyelocytic leukemia (APL), HIF-1α collaborates with the PML-RARα fusion protein to maintain leukemia stem cell self-renewal and promote tumor neovascularization and migration." (PMID 40791591, 2025). "Previous studies have shown that echinomycin inhibits HIF1-α activity in lymphoma and leukemia stem cell models, considerably boosting survival in mouse models and hindering cancer cell progression and proliferation." (PMID 39994019, 2025). "Although the co-localization of ASH1L and HIF-1α found in both metastatic tumors and leukemia suggests a universal mechanism of gene regulation, their co-target genes in metastatic cells are distinct from those in leukemia." (PMID 40394007, 2025). "In particular, other studies have indicated its effect on HEL leukemia cells, showcasing its ability to inhibit VEGF expression, reduce HIF-1α levels, and impede angiogenesis within this leukemia cell model." (PMID 39335148, 2024). "Here, we found that both HIF1α and HIF2α exert leukemia‐promoting functions in models of established AML (i.e., cell lines and PDX)." (PMID 37807875, 2023). "The role of HIF-1A in cancer is well reported, and HIF-1A was found to be upregulated in various types of leukemia." (PMID 37624039, 2023). "Inhibition of hypoxia-induced HIF1α signaling can also promote leukemia progression by helping cells adapt to hypoxic conditions in the BM environment and promoting chemoresistance." (PMID 37532715, 2023). "Taken together, under hypoxic conditions leukemia cells express HIF1α and display reduced population doubling, what implicates that functioning of cells is different in these conditions." (PMID 37123244, 2023).
leukemia (continued). "Most of the genes in the HIF1A module play leukemia-promoting roles in AML, such as HIF1A, CEBPG, JUN, and ATF4." (PMID 37691822, 2023). "Overall, we observed that while HIF1α had minor effects on leukemia progression, reduction of HIF2α affected leukemia expansion in both PDX models, albeit in different compartments." (PMID 37807875, 2023). "HIF-1α stabilization promotes drug resistance in multiple leukemias, suggesting that HIF-1α stabilization protected against LCL-805 cytotoxicity." (PMID 38136410, 2023). "A dual activity of HIF1α in supporting proliferation of leukemia bulk and maintenance of leukemia-repopulating cells was also observed in T-ALL." (PMID 36059690, 2022). "Following these reports, HIFα factors, prevalently HIF1α, have been attributed other important tumor-promoting functions, with some leukemia-specific nuances." (PMID 36059690, 2022). "It has already been mentioned that HIF1α can regulate the TGFβ, Wnt, and Notch signaling pathways to promote the survival of leukemia cells." (PMID 35847841, 2022). "One of the first reports of HIF1α upregulation in leukemia came from studies in chronic myeloid leukemia (CML), where it was observed that BCR-ABL induces HIF1α mRNA and protein expression downstream PI3K/mTOR activation." (PMID 36059690, 2022). "Rather, in the case of MLL-AF9-driven leukemia, HIF1α deletion accelerated leukemia progression by increasing cell proliferation." (PMID 36059690, 2022). "In this disease, it was first observed that HIF1α is highly expressed at the mRNA and protein level compared to normal B cells, which correlates with leukemia progression." (PMID 36059690, 2022). "It has been demonstrated that HIF-1α plays a role in the phenomenon of leukemogenesis by interacting with AML1/ETO protein to prime leukemia cells for subsequent aggressive growth." (PMID 36231060, 2022). "In contrast, we demonstrated an essential role of HIF1α under normoxia in leukemia/lymphoma stem cells, which is efficiently targeted by echinomycin, an inhibitor of HIF1α transcriptional activity." (PMID 34470658, 2021). "Hypoxia-mediated signaling through the transcription factor HIF-1α is required for the maintenance of leukemia-initiating cells in vitro and in vivo, suggesting a pivotal role for hypoxia in sustaining leukemia." (PMID 34066861, 2021). "The importance of HIF-1α in leukemia microenvironment is given by the fact that it has an important role in differentiation and growth of stem cells, maintaining also the ability of HSC to regulate ROS and to keep a quiescence state." (PMID 34026651, 2021). "Although more studies are required to better clarify the regulatory network involving GATA-1 and HIF-1α in normal and aberrant hematopoiesis, these finding shed new light on the molecular mechanisms leading to metabolic rewiring in leukemia cells." (PMID 34679737, 2021). "Contrary to the notion that hypoxia is a major contributor to leukemia progression, HIF-1α is also considered to have a suppressive function in leukemogenesis." (PMID 34066861, 2021). "Our studies identified that HIF-1α stabilization in stromal cells of the microenvironment facilitates leukemia homing and progression." (PMID 32695673, 2020). "The ATLAS RNAseq revealed that HIF-1α expression was higher in the Raji cell line than in leukemia or DLBCL." (PMID 32403237, 2020). "This study thus identified a novel small molecule that rapidly kills MLL-rearranged leukemia cells by targeting a metabolic vulnerability in a subset of low HIF1α/low MEIS1-expressing MLL-rearranged leukemia cells." (PMID 30670779, 2019). "Silencing of HIF1α expression sensitized an intrinsically unresponsive MLL-rearranged leukemia cell to CCI-006, indicating that this pathway plays a role in determining sensitivity to the compound." (PMID 30670779, 2019). "It is now postulated that one of the leukemia-driving roles of MEIS1 entails regulating metabolic phenotype through regulating the transcription of HIF1α." (PMID 30670779, 2019).